CD36 (CD36 molecule (CD36 blood group))
Description:
Multifunctional glycoprotein that acts as a receptor for a broad range of ligands. Ligands can be of proteinaceous nature like thrombospondin, fibronectin, collagen or amyloid-beta as well as of lipidic nature such as oxidized low-density lipoprotein (oxLDL), anionic phospholipids, long- and very long-chain fatty acids and bacterial diacylated lipopeptides. They are generally multivalent and can therefore engage multiple receptors simultaneously, the resulting formation of CD36 clusters initiates signal transduction and internalization of receptor-ligand complexes. The dependency on coreceptor signaling is strongly ligand specific. Cellular responses to these ligands are involved in angiogenesis, inflammatory response, fatty acid metabolism, taste and dietary fat processing in the intestine (Probable). Binds long- and very long-chain fatty acids and facilitates their transport into cells, thus participating in muscle lipid utilization, adipose energy storage, and gut fat absorption (By similarity). Mechanistically, palmitoylated CD36 captures fatty acids on the cell surface, the binding of fatty acids activates downstream kinase LYN, which phosphorylates the palmitoyltransferase ZDHHC5 and inactivates it, resulting in the subsequent depalmitoylation of CD36, a step needed to initiate the endocytic process and delivery of fatty acids into the cell. In the small intestine, plays a role in proximal absorption of dietary fatty acid and cholesterol for optimal chylomicron formation, possibly through the activation of MAPK1/3 (ERK1/2) signaling pathway (By similarity). Involved in oral fat perception and preferences. Detection into the tongue of long-chain fatty acids leads to a rapid and sustained rise in flux and protein content of pancreatobiliary secretions (By similarity). In taste receptor cells, mediates the induction of an increase in intracellular calcium levels by long-chain fatty acids, leading to the activation of the gustatory neurons in the nucleus of the solitary tract (By similarity). Important factor in both ventromedial hypothalamus neuronal sensing of long-chain fatty acid and the regulation of energy and glucose homeostasis (By similarity). Receptor for thrombospondins, THBS1 and THBS2, mediating their antiangiogenic effects (By similarity). Involved in inducing apoptosis in podocytes in response to elevated free fatty acids, acting together with THBS1 (By similarity). As a coreceptor for TLR4:TLR6 heterodimer, promotes inflammation in monocytes/macrophages. Upon ligand binding, such as oxLDL or amyloid-beta 42, interacts with the heterodimer TLR4:TLR6, the complex is internalized and triggers inflammatory response, leading to NF-kappa-B-dependent production of CXCL1, CXCL2 and CCL9 cytokines, via MYD88 signaling pathway, and CCL5 cytokine, via TICAM1 signaling pathway, as well as IL1B secretion, through the priming and activation of the NLRP3 inflammasome (By similarity). Selective and nonredundant sensor of microbial diacylated lipopeptide that signal via TLR2:TLR6 heterodimer, this cluster triggers signaling from the cell surface, leading to the NF-kappa-B-dependent production of TNF, via MYD88 signaling pathway and subsequently is targeted to the Golgi in a lipid-raft dependent pathway (By similarity). (Microbial infection) Directly mediates cytoadherence of Plasmodium falciparum parasitized erythrocytes and the internalization of particles independently of TLR signaling.
Synonyms: FAT; GPIIIB; GPIV; GP3B; GP4; SCARB3; BDPLT10; CHDS7; PASIV
Tractability: Antibody: UniProt places it where antibodies can reach, with high confidence; its Gene Ontology location is reachable by antibodies, with high confidence; UniProt predicts a signal peptide or a membrane-spanning region. PROTAC: UniProt records ubiquitination sites on it; ubiquitination databases record sites on it; its protein half-life has been measured.
Target class: Membrane receptor
Safety:
Unwanted effects reported when the protein is acted on. In parentheses: how it was acted on, where the effect was seen, and who reports it.
Increased, Liver Steatosis (activation; source: AOP-Wiki)
Accumulation, Liver lipid (activation; source: AOP-Wiki)
N/A, Liver Steatosis (activation; source: AOP-Wiki)
Gene: Protein-coding gene on chromosome 7 (80,369,532 to 80,679,277, forward strand). Ensembl gene ENSG00000135218.
Subcellular location: Cell membrane; Membrane raft; Golgi apparatus; Apical cell membrane
Subcellular location (Human Protein Atlas): Golgi apparatus
Pathways (Reactome):
Immune System: Cross-presentation of particulate exogenous antigens (phagosomes); ER-Phagosome pathway; Interleukin-4 and Interleukin-13 signaling; MyD88:MAL(TIRAP) cascade initiated on plasma membrane; Neutrophil degranulation; Regulation of TLR by endogenous ligand; Toll Like Receptor TLR6:TLR2 Cascade
Disease: IRAK4 deficiency (TLR2/4); MyD88 deficiency (TLR2/4)
Metabolism: Intracellular metabolism of fatty acids regulates insulin secretion; PPARA activates gene expression
Developmental Biology: Transcriptional regulation of white adipocyte differentiation
Gene expression (Transcription): MLL4 and MLL3 complexes regulate expression of PPARG target genes in adipogenesis and hepatic steatosis
Hemostasis: Platelet degranulation
Vesicle-mediated transport: Scavenging by Class B Receptors
Gene Ontology:
Molecular function: amyloid-beta binding; lipid binding; lipoprotein particle binding; long-chain fatty acid transmembrane transporter activity; low-density lipoprotein particle binding; low-density lipoprotein particle receptor activity; oleate transmembrane transporter activity; oxidised low-density lipoprotein particle receptor activity; protein binding; protein-containing complex binding; scavenger receptor activity; short-chain fatty acid transmembrane transporter activity; signaling receptor activity; thrombospondin receptor activity; Toll-like receptor binding; cargo receptor activity; transforming growth factor beta binding; high-density lipoprotein particle binding; lipoteichoic acid immune receptor activity
Biological process: amyloid-beta clearance by cellular catabolic process; cellular response to amyloid-beta; cellular response to diacyl bacterial lipopeptide; cellular response to oxidised low-density lipoprotein particle stimulus; cholesterol import; fatty acid transport; inflammatory response; lipid storage; lipid transport across blood-brain barrier; lipoprotein transport; long-chain fatty acid import across plasma membrane; long-chain fatty acid import into cell; long-chain fatty acid transport; low-density lipoprotein particle clearance; negative regulation of angiogenesis; nitric oxide-cGMP-mediated signaling; oxidised low-density lipoprotein particle clearance; positive regulation of canonical NF-kappaB signal transduction; positive regulation of cell-matrix adhesion; positive regulation of macrophage derived foam cell differentiation; positive regulation of toll-like receptor 4 signaling pathway; receptor-mediated endocytosis; regulation of protein-containing complex assembly; regulation of toll-like receptor signaling pathway; short-chain fatty acid transport; and 45 more
Cellular component: cell periphery; cell surface; extracellular region; Golgi apparatus; membrane raft; plasma membrane; receptor complex; brush border membrane; caveola; endocytic vesicle membrane; membrane; phagocytic vesicle; platelet alpha granule membrane; specific granule membrane; apical part of cell; apical plasma membrane; external side of plasma membrane
Genetic constraint (gnomAD): Loss-of-function variants: 34 observed, 20.12 expected, observed/expected ratio (o/e) 1.69, 90% interval 1.26 to 1.95. The upper end of that interval is the gene's LOEUF score, 1.95, which puts it in group 6 of 6, group 1 being the genes least tolerant of losing a copy. Missense variants: 326 observed, 247.62 expected, observed/expected ratio (o/e) 1.32, 90% interval 1.2 to 1.44. Synonymous variants: 71 observed, 89.38 expected, observed/expected ratio (o/e) 0.79, 90% interval 0.65 to 0.97.
Homologues: Orthologues: chimpanzee CD36 (99% identical), macaque CD36 (95% identical), rabbit CD36 (89% identical), rat Cd36-ps1 (87% identical), mouse Cd36 (84% identical), pig CD36 (83% identical), dog CD36 (82% identical), guinea pig CD36 (81% identical), tropical clawed frog cd36 (54% identical), zebrafish cd36 (51% identical), tropical clawed frog cd36l (48% identical), Caenorhabditis elegans scav-2 (30% identical), and 2 more. Paralogues in human: SCARB2 (33% identical), SCARB1 (31% identical).
Diseases named in the same sentence as CD36 in open-access papers:
CD36 is named in the same sentence as 428 diseases in open-access papers, as found by Europe PMC text mining. Sharing a sentence is not in itself a finding about the gene and the disease. The quoted sentences say what the papers report.
atherosclerosis (395 papers, 2004 to 2026). A disease characterized by the build-up of fatty material and calcium deposition in the arterial wall resulting in partial or complete occlusion of the arterial lumen. "The differentially expressed gene CD36 was found to be associated with glucose intolerance, atherosclerosis, arterial hypertension, diabetes, and so on." (PMID 41584930, 2026). "The Class B SR member, CD36, is heavily implicated in atherosclerosis, and potentially in cancer progression." (PMID 40563926, 2025). "Previous research has shown that clinically CD36-deficient patients exhibit hyperlipidemia, insulin resistance, fatty liver, and atherosclerosis." (PMID 40110132, 2025). "The inhibition of CPT1 in macrophages is linked to the progression of atherosclerosis, as it increases the production of CD36, a protein involved in LDL absorption." (PMID 40099271, 2025). "The discovery that VAV induces foam cell formation and the progression of atherosclerotic plaques via CD36 signaling is critical for understanding the molecular mechanisms underlying atherosclerosis." (PMID 39445733, 2025). "Despite CD36 being associated with lipid uptake and foam cell formation in atherosclerosis, our findings highlight a contrasting role in CAS, where it mediates proinflammatory signaling and HCASMC hyperreactivity." (PMID 41011253, 2025). "Considering the pivotal role of metabolic imbalance in cholesterol as a constituent cause of atherosclerosis, we investigated the concentrations of proteins affiliated with cholesterol absorption and discharge, inclusive of CD36, SR‐A1, ABCA1, and ABCG1." (PMID 39804798, 2025). "Single nucleotide variants (SNVs) such as rs3211938, rs3173798, and rs1761667 have been linked to T2DM and atherosclerosis by altering CD36 expression and function, potentially affecting lipid profiles and contributing to cardiovascular risk." (PMID 40867895, 2025). "Macrophage uptake of lipids through the scavenger receptor CD36 is associated with altered macrophage functions and disease pathogenesis in obesity and atherosclerosis 16–19." (PMID 40502773, 2025). "In conclusion, disturbed flow induced a distinct senescence CD36+ endothelial cell population, and this senescent cell population was closely associated with the progression of atherosclerosis and plaque hemorrhage." (PMID 40594772, 2025). "Under chronic inflammation, oxidant stress, hyperlipidemia, or diabetes, CD36 deficiency alleviates atherosclerosis and thrombosis to maintain homeostasis." (PMID 41011253, 2025). "Third, butyrate slows the progression of atherosclerosis, which is linked to the reduction in CD36 levels in macrophages and endothelial cells, decline in pro-inflammatory cytokine levels, and lower nuclear factor-κB activation level." (PMID 40525114, 2025). "Consistent with its role in chronic inflammatory diseases such as atherosclerosis, CD36 modulation was associated with reduced systemic inflammation and increased differentiation of vascular macrophages towards an M2 anti‐inflammatory phenotype." (PMID 39552437, 2024). "As coreceptor, CD36 is linked to the immune response and physio‐pathological conditions which share inflammation as a common feature, including atherosclerosis, atherothrombosis, diabetes, stroke, Alzheimer's disease, angiogenesis, and cancer." (PMID 39552437, 2024). "CD36 is implicated in a myriad of neuropathological processes, including cerebral ischemia, neurovascular dysfunction, and atherosclerosis." (PMID 38840180, 2024). "Three pivotal atherosclerosis-associated genes—CD36, S100A10, CSNK1A1—were unveiled, offering valuable clinical insights." (PMID 39660117, 2024). "CD36 internalizes oxidized LDL (Ox-LDL) mediating the formation of foam cells in macrophages increasing the risk of atherosclerosis." (PMID 39114568, 2024).
atherosclerosis (continued). "In summary, capsaicin treatment reduces atherosclerosis development, which is linked with decreased macrophage recruitment and CD36 expression in lesions, suggesting its role in inhibiting foam cell formation." (PMID 39339767, 2024). "Two members of the class B scavenger receptor family, cluster of differentiation 36 (CD36) and scavenger receptor class B type 1 (SR-B1), play central roles in lipoprotein metabolism and have been implicated in atherosclerosis." (PMID 37625590, 2023). "CD36 is closely associated with the progression of cardiovascular diseases because CD36 is decreased in pathological cardiac hypertrophy caused by ischemia–reperfusion and pressure overload and increased in diabetic cardiomyopathy and atherosclerosis." (PMID 40625574, 2023). "PCSK9 blocking agents reduce systemic levels of total cholesterol and LDL, affecting the risk of atherosclerosis but also reducing the supply of cholesterol by cancer cells through the enhancement of apolipoprotein E receptor, CD36, β-secretase 1, and others." (PMID 36900189, 2023). "CD36 has been implicated in atherosclerosis by promoting foam cell formation in the intima of blood vessels." (PMID 36903257, 2023). "Levels of CD36, a scavenger receptor implicated in atherosclerosis, and F4/80, a macrophage marker in small intestine, were quantified by quantitative real-time PCR." (PMID 35684000, 2022). "Polymorphisms and defects in FAT/CD36 transcription and translation alter normal lipid metabolism, producing obesity, metabolic syndrome, atherosclerosis, arterial hypertension, diabetes, cardiomyopathy, Alzheimer’s disease, and multiple sclerosis." (PMID 36615118, 2022). "This is mediated in part via up-regulation of the macrophage ox-LDL receptors SRA1 and CD36, highlighting a novel mechanism through which lncRNA can target miRNA implicated in atherosclerosis." (PMID 35758143, 2022). "For example, in atherosclerosis, PPARγ promotes the expression of CD36, causing enhanced uptake of lipids by macrophages; it also accelerates cholesterol efflux by upregulating the expression of ABCA1 and ABCG1." (PMID 35432274, 2022). "In summary, our current study demonstrated that vimentin-deficient macrophages uptake less oxLDL via decreased membrane localization of CD36 and thus CD36-deficiency in macrophages reduces development of atherosclerosis." (PMID 35656400, 2022). "Under environmental or genetic conditions that promote chronic inflammation, oxidant stress, hyperlipidemia, and/or diabetes, CD36 deficiency has profound protective effect on atherosclerosis and thrombosis, pointing to important roles in homeostasis." (PMID 35438721, 2022). "Lack of TAKI in mice can reduce the inflammation of adipose tissue, loss of mitochondrial function, reduce the formation of CD36 and foam cells, and then cause atherosclerosis." (PMID 33722242, 2021). "In summary, CD36, associated with prediabetes and atherosclerosis, is expressed at the cellular membranes of platelets and macrophages, in a soluble form, or exosomes." (PMID 33921168, 2021). "Animal studies performed on CD36‐deficient mice suggest that deficiency of CD36 prevents the development of atherosclerosis." (PMID 33830664, 2021). "Deficiency in CD36 has been shown to be reduce proinflammatory signaling, cell recruitment, Ccl2 and Vcam1 levels in models of ischemic stroke and atherosclerosis." (PMID 34496918, 2021). "Conscious of the potential confounding impact of the loss of CD36 in macrophages and other hematopoietic cells on atherosclerosis development and systemic inflammation, we created an EC CD36° using the Tie2e cre, which spares these cells." (PMID 34888367, 2021). "CD36 has been implicated in numerous health conditions, such as obesity, dyslipidemia, atherosclerosis, and AD." (PMID 34283828, 2021).